NOD2 (nucleotide binding oligomerization domain containing 2)
Diseases named in the same sentence as NOD2 in open-access papers (continued):
Sharing a sentence is not in itself a finding about the gene and the disease.
Crohn disease (continued). "It is conceivable that targeting TRIM27 might be advantageous when NOD2 activity is altered, such as in Crohn's disease." (PMID 22829933, 2012). "While this evidence showed a plausible mechanism by which NOD2 variants contributed to the onset of Crohn's disease, these findings have not been replicated in human studies, and further data has been published that confirm the loss-of-function mechanism." (PMID 23119165, 2012). "Studies have revealed that some individuals with familial Crohn’s disease, a chronic inflammatory condition of the gut, have mutations in the Card15 gene encoding NOD2, but not NOD1." (PMID 23162548, 2012). "Although it is unclear how these mutations contribute to intestinal disease and whether Nod2 binds MDP directly, these findings reinforce an important role for bacteria in Crohn’s disease." (PMID 21994779, 2011). "Genome-wide association studies (GWAS) have revealed small nucleotide polymorphisms (SNPs) in autophagy genes such as ATG16lL and in additional genes now known to influence autophagic processing (i.e., NOD2 and IRGM) associated with susceptibility to Crohn's disease." (PMID 22190939, 2011). "The occurrence of ASCA was higher by 25% in Crohn's disease patients carrying at least one NOD2/CARD15 mutation as compared to the non-carrier ones; however, the ASCA prevalence was also high in this latter group." (PMID 20886039, 2010). "A potential role of L. monocytogenes in the pathogenesis of inflammatory bowel disease (IBD) has been suggested, because interference of the pathogen with NOD2-based signaling, and variations of NOD2/CARD15 have been shown to represent a risk factor for Crohn's disease." (PMID 21188219, 2010). "There could also be a connection of Nod2 to Crohn's disease as muramyl dipeptide (MDP) protects mice from experimental colitis by down regulating TLR2 and other TLRs in DCs." (PMID 20949035, 2010). "This situation would be similar to the role of NOD2 in Crohn's disease, in which wild type NOD2, also a member of the NLR family, inhibits TLR2 (toll-like receptor-2) activation by peptidoglycan, while mutated NOD2 fails to inhibit TLR2, leading to chronic inflammation in the bowel." (PMID 20041150, 2009). "The co-existence of several allelic variant of TLR4, NOD2/CARD15 and HSP70-2 genes may be associated with severe form of the Crohn's disease among the Tunisian population." (PMID 19664207, 2009). "Furthermore, mycobacterial TLR2 and NOD2 agonists synergistically induce cytokine release in PBMCs obtained from healthy volunteers and patients with Crohn's disease." (PMID 17705850, 2007). "The lack of an association between Crohn's disease-associated NOD2 gene mutations and tuberculosis in African patients does not exclude a role for NOD2 in MTB-infection because NOD2 gene mutations are probably rare in African populations." (PMID 17705850, 2007). "For example, the CARD15 gene product, NOD2, influences the development of the adaptive immune response and functional variants of the gene predispose to the inflammatory bowel disease (IBD), Crohn disease." (PMID 16519819, 2006). "Therefore, intestinal CCL20 induction via multiple alternative pathways may outweigh genetic defects in the NOD2 pathway in Crohn’s disease." (PMID 40542081, 2025). "Notably, this synergy is absent in macrophages from Crohn’s disease patients harboring non-functional NOD2 variants, underscoring the critical role of VD in bridging NOD2-mediated immune responses and inflammation regulation." (PMID 40728969, 2025). "In addition, NOD2 helped to mediate immune tolerance and homeostasis by inhibiting TLR2/4-mediated induction of inflammatory cytokine production, which is strongly associated with Crohn’s disease (CD)." (PMID 34971392, 2022).
Crohn disease (continued). "In Crohn’s disease, nucleotide-binding oligomerization domain (NOD) 2 (NOD2), the first identified susceptibility gene, is also reduced by nicotine in HT29 cells when treated by TNF-α, implying the potential anti-inflammatory effect of nicotine on Crohn’s disease." (PMID 35251010, 2022). "It had been previously shown that a lack of NOD2 signalling could increase Crohn's disease susceptibility using mouse models." (PMID 34268854, 2021). "NOD2 mutations plays a major role in the pathogenesis of noninfectious granulomatous diseases, including sarcoidosis and Crohn’s disease (CD), which might be accompanied by pulmonary manifestations and lung damage." (PMID 34440800, 2021). "Hence, the involvement of NOD2 in maintaining intestinal equilibrium is also likely essential for liver inflammation, albeit indirectly, as susceptibility to SBP is increased in patients with Crohn’s disease." (PMID 29872030, 2019). "Yet, the mechanism of Crohn’s disease via NOD2 mutation is not entirely understood." (PMID 31723489, 2019). "Absence of extraintestinal symptoms in patients with Crohn's disease may be associated with the absence of CARD15/NOD2 SNPs." (PMID 30648106, 2018). "These conditions include hereditary auto‐inflammatory syndromes associated with activating mutations in NOD2, such as early‐onset sarcoidosis and Blau syndrome, and early‐onset inflammatory bowel disease, in particular Crohn's disease where NOD2 signaling may play an important role." (PMID 30026309, 2018). "Importantly, Nod2 is involved in the pathogenesis of Crohn’s disease." (PMID 24634797, 2013). "Contrarily, in the mucosa where NOD2 is mutated the negative feedback is absent and the peptidoglycan is able to trigger a Th1 cell-mediated inflammation which leads to the development of Crohn's disease." (PMID 23971052, 2013). "Thus, cells over expressing a mutated NOD2 variant associated with Crohn’s disease failed to induce hBD-2 via NF-κB." (PMID 25436887, 2013). "In another mouse model, a NOD2 mutation potentiated NF-κB activity and IL-1β processing, suggesting that NOD2 may act as a positive regulator of NF-κB activation and IL-1β secretion, thereby increasing the intestinal inflammation observed in Crohn’s disease patients." (PMID 23162548, 2012). "Later, two other NOD2 transgenic mice were engineered: one with an insertion causing a frameshift mutation in the final LRR domain, corresponding to one of the most frequent mutation observed in familial Crohn’s disease patients, and another with a loss-of-function insertion in the Card15 locus." (PMID 23162548, 2012). "At least three mutations in the gene encoding nucleotide-binding oligomerization domain 2 (NOD2), also known as CARD15, including small nucleotide polymorphisms (R702W and G908R) and a frameshift mutation (L1007fsinsC) have been found in association with Crohn's disease." (PMID 22190939, 2011). "At the time of initial CD diagnosis she had presented with oesophagitis, focal active gastritis, granulomatous colitis consistent with CD in the colon, and chronic active proctitis, however, the role of NOD2 triple mutation in this multiple disease presentation is not clear." (PMID 21079743, 2010). "However, the Nod2-deficient mice do not reflect the human genetic variants associated with Crohn’s disease, and the results shown herein might therefore not be directly transferrable into the clinical setting." (PMID 37240707, 2023). "The expression levels of both NOD2 and activated/phosphorylated RIPK2 are upregulated in pediatric patients with active Crohn’s disease or ulcerative colitis." (PMID 35625613, 2022). "Our findings indicate that deleterious NOD2 variants should be considered as strong predictors of IBD-CD onset and implicate NOD2 as a Mendelian disease gene for early onset IBD, specifically for a molecularly defined subset of Crohn’s disease patients." (PMID 33692434, 2021).
Crohn disease (continued). "Interestingly, increasing evidence has shown that NOD2 stimulation impairs autophagy response in dendritic cells and that increased activation of autophagy related 16 like 1 (ATG16L1) signaling upregulates the induction of deficient autophagy in Crohn’s disease." (PMID 33670592, 2021). "Genetic variations in NOD1/CARD4 and/or NOD2/CARD15 have previously been identified in many diseases such as inflammatory bowel disease, Crohn’s disease, sarcoidosis, non-Hodgkin lymphoma, cancer and RA." (PMID 32578848, 2020). "Recent studies have found a strong interrelationship between the NOD2 gene, previously known as caspase recruitment domain-containing protein 15 (CARD15), and Crohn’s disease." (PMID 31723489, 2019). "Decreased macroautophagy due to NOD2 and ATG16L1 mutations may impair innate resistance to invading bacteria and, thereby, trigger inflammation as a result of increased antigenic load or lead to insufficient tolerance induction against commensals in the gut and trigger Crohn’s disease." (PMID 29515999, 2018). "The co‐involvement of NOD2, JAK2, MUC19 and MST1 in mucosal defence and inflammation in Crohn's disease therefore deserves further study." (PMID 29441677, 2018). "Crohn’s disease is one of the most common types of IBD, which makes the NOD2-G908R cell line a useful model to investigate potential functional foods to alleviate symptoms of IBD." (PMID 30200338, 2018). "We identified TRIM27 as a negative regulator of NOD2-mediated inflammatory responses and detected enhanced TRIM27 expression in the colon of Crohn's disease patients." (PMID 22829933, 2012). "Collectively, these data support a role for TRIM27 as a specific negative regulator of NOD2-mediated signaling and suggest a implication of TRIM27 in Crohn's disease." (PMID 22829933, 2012). "We found that TRIM27 expression is increased in Crohn's disease patients, underscoring a physiological role of TRIM27 in regulating NOD2 signaling." (PMID 22829933, 2012). "Thirty non-conservative mutations associated with Crohn's disease have been identified within the NOD2 gene, but only three are common, namely those leading to the Arg702Trp and Gly908Arg substitutions, and a frame shift mutation (3020insC→1007fs) resulting in a truncated version of NOD2." (PMID 21625457, 2011). "Furthermore, patients with Crohn’s disease or ulcerative colitis exhibited elevated RIPK2 expression, while NOD2 expression remained unchanged in these conditions." (PMID 40406369, 2025). "Similarities have been shown between the effects of carrageenan and changes in the NOD2/CARD15 gene, which are predisposing factors for Crohn’s disease via LPS activation of Gram-negative bacteria." (PMID 38732613, 2024). "When NOD2 was shown to recognize MDP, an experimental system to overexpress the NOD2 genes into HEK293 cells was used, in which the mutant with a frameshift in the LRR frequently identified in Crohn’s disease was shown to be hyporesponsive to MDP." (PMID 35711422, 2022). "Together these data suggest that autophagy is a key pathway linking NOD2 and ATG16L1 in the development of Crohn’s disease and hint that XIAP may also have some role in autophagy regulation." (PMID 29743550, 2018). "Susceptibility to several immune-related diseases, including Crohn’s disease, colorectal and breast cancers, and graft-versus-host-disease (GVHD) showed a correlation with genetic variants of NOD2 in Caucasian, but not in Japanese, populations." (PMID 29165176, 2017). "rs9302752 lies between NOD2 and SNX20 in a susceptibility locus for leprosy but not Crohn’s disease, and has been presumed to predispose to leprosy via altering NOD2 expression." (PMID 27015630, 2016). "In addition, the French group sequenced the coding regions of NOD2 in 457 patients with Crohn’s disease and 103 unaffected individuals to identify rare nonsynoymous variants." (PMID 32948841, 2021).
Crohn disease (continued). "For example, the NOD2-specific agonist muramyl dipeptide promoted TNF-α secretion from MCs and, in vivo, a significant increase in NOD2 positive MCs was reported in colonic mucosal biopsies from Crohn ́s disease patients compared to those coming from ulcerative colitis or control biopsies." (PMID 34211473, 2021). "Thus, our data indicate that Crohn's donor DCs show defective cross-presentation following NOD2 stimulation and may indicate aberrant intestinal CD8+ T cell responses detected in the mucosa in Crohn's disease." (PMID 31114588, 2019). "In this study, we investigated whether administration of MIS416, a novel microparticle that activates NOD2 and TLR9 signaling, could enhance the therapeutic efficacy of hUCB-MSCs against Crohn’s disease, using dextran sulfate sodium (DSS)-induced colitis model." (PMID 29892282, 2018). "It has been suggested that the inflammatory response seen in Crohn's disease results from the inability of toll-like receptor-2 (TLR-2) to become tolerant to its ligand in the absence of appropriately functioning NOD2, resulting in upregulation of proinflammatory cytokines." (PMID 23119165, 2012). "The lack of NOD2-dependent Th2 differentiation in a subset of Crohn’s disease patients might explain how the Th1-mediated inflammation at the intestinal mucosa contributes to the pathogenesis of the disease." (PMID 23162548, 2012). "No SNPs were confirmed for the CARD15/NOD2 gene fragment, but a substitution (T>C) was found in the DLG5 gene in a Crohn's disease patient." (PMID 30648106, 2018).
Blau syndrome (150 papers, 2008 to 2026). "Blau syndrome is a rare autoinflammatory disorder caused by gain-of-function mutations in the NOD2 (nucleotide binding oligomerization domain containing 2 receptor) gene." (PMID 41601685, 2026). "A targeted genetic investigation identified a de novo pathogenic variant in the NOD2 gene, confirming the diagnosis of Blau Syndrome." (PMID 40881804, 2025). "Cryopyrin-associated periodic syndrome (CAPS), an autosomal dominant disease, is caused by NLRP3, and Blau syndrome, an autosomal dominant disease, is caused by NOD2 mutations." (PMID 40282361, 2025). "Blau syndrome (BS) is an autoinflammatory disease of the skin, eyes, and joints underpinned by excessively signaling NOD2 variants." (PMID 40613780, 2025). "Patient 6 had the germline p.D512Y mutation in the NOD2 gene and in retrospect the phenotype was compatible with Blau syndrome." (PMID 40538939, 2025). "Blau syndrome (BS) is a rare inherited systemic disorder, attributed to a gain-of-function mutation in the nucleotide-binding oligomerization domain (NOD2) gene, which results in the upregulation of pro-inflammatory cytokines." (PMID 40766917, 2025). "The results, albeit preliminary and affected by the sample size, do not allow a definitive conclusion on a monogenic disease caused by mutation in NOD2, with the obvious exception of Blau syndrome." (PMID 40196132, 2025). "In contrast, Blau syndrome is characterized by gain-of-function mutations primarily concentrated within the NBD region of NOD2, leading to excessive activation of NOD2 and subsequent NF-κB activation independent of MDP." (PMID 39329913, 2024). "Mutations in NOD2 have been implicated in Yao syndrome, inflammatory bowel diseases, and Blau syndrome." (PMID 39006711, 2024). "Blau syndrome is characterized by dermatitis, arthritis, and uveitis related to NOD2 mutation, but in recent years, granulomatous lesions other than the triad of BS have also been considered as a phenotype of BS." (PMID 38933100, 2024). "Here, we described a girl with symptomatic renal arteritis against the background of Blau syndrome with an M513T de-novo variant in NOD2." (PMID 36915122, 2023). "Blau syndrome is a rare autoinflammatory disease caused by autosomal dominant mutations in the CARD15/NOD2 gene." (PMID 36915122, 2023). "NOD2 variants classified as pathogenic for BLAU syndrome or with an high prevalence in healthy population (polymorphisms) were excluded." (PMID 37848930, 2023). "In overexpression systems using plasmids expressing Blau syndrome-associated NOD2 mutants transfected into HEK293 cells, ligand-independent NF-κB activation was observed." (PMID 37415984, 2023). "NOD2 mutation is also associated with many other important diseases except CD, such as Blau syndrome, asthma, arthritis and CRC30–33,47." (PMID 37286542, 2023). "For this evaluation, we used iPS-ML cell lines established from a Blau syndrome patient; one line had the p.R334W mutation in NOD2 and the other mutation was corrected back to WT by CRISPR-Cas9–mediated targeting." (PMID 37415984, 2023). "Blau syndrome (BS) is a monogenic disorder caused by NOD2 gene variants characterized by the triad of granulomatous polyarthritis, rash, and uveitis." (PMID 37576148, 2023). "While most NOD2 mutations associated with Blau syndrome development are thought to be gain-of-function, there are also reports pointing to NOD2 loss-of-function in Blau syndrome development." (PMID 37869013, 2023). "Blau syndrome is an autosomal dominant disorder due to NOD2 mutations, of which over 15 have been identified." (PMID 37250639, 2023). "Blau syndrome (BS), first described by Edward Blau in 1985, is a rare autosomal dominant, granulomatous, autoinflammatory disease caused by mutations in the NOD2/CARD15 gene." (PMID 36915122, 2023). "Blau syndrome was caused by gain-of-function variants in NOD2 gene, which lead to an aberrant auto-activation of the NF-κB pathway." (PMID 37711606, 2023).